CNTNAP2 (contactin associated protein 2)
Diseases named in the same sentence as CNTNAP2 in open-access papers (continued):
Sharing a sentence is not in itself a finding about the gene and the disease.
epilepsy (continued). "Since then, mutations in the CNTNAP2 gene, encoding Caspr2, have been associated with a range of neurodevelopmental cognitive disorders including autism spectrum disorder (ASD), dyslexia and language impairment, epilepsy, and schizophrenia (5, –, 8)." (PMID 32675284, 2020). "Variants in CNTNAP2 and MEF2C were correlated with epilepsy/tics in cases." (PMID 30763456, 2019). "Both loci include multiple potential candidate genes, including IGF1R, CNTNAP2, and DPP6, all are well‐studied genes that are strongly associated with developmental and speech delays, congenital heart disease, epilepsy, diaphragmatic hernia, renal anomalies, and ID." (PMID 31475484, 2019). "We are the first to show that rare functional variants of CNTNAP2 and MEF2C could significantly increase the risk of comorbid epilepsy/tics in nonsyndromic ASD patients, which should have a significant impact on ASD patient management." (PMID 30763456, 2019). "In ASD cases with epilepsy or tics, 25.81% and 9.68% carried rare functional variants in CNTNAP2 and MEF2C, respectively, whereas in ASD cases without epilepsy or tics, only 2.78% and 0% carried rare functional variants in CNTNAP2 and MEF2C, respectively." (PMID 30763456, 2019). "Although the father was affected by Brugada syndrome (BrS) and epilepsy and carried this variant, the absence of this complex phenotype and the lack of expression of the CNTNAP2 gene in the heart complicate the association between this variant and SUDEP." (PMID 29261713, 2017). "Heterozygous copy-number and missense variants in CNTNAP2 and NRXN1 have repeatedly been associated with a wide spectrum of neuropsychiatric disorders such as developmental language and autism spectrum disorders, epilepsy and schizophrenia." (PMID 21827697, 2011). "Other described mutations include CNTNAP2 (Contactin-associated protein-like 2) and SCN1A (sodium channel, voltage-gated, type I, alpha subunit), which might point that EAF pertains to the spectrum of SCN1A-related epilepsy." (PMID 35153984, 2021). "A study by our group that included 20 epilepsy patients with personal or family history of heart rhythm disturbance/cardiac arrhythmia/sudden death identified four missense variants in epilepsy genes CDKL5, CNTNAP2, GRIN2A, and ADGRV1, with complete segregation within the family." (PMID 31018519, 2019). "In addition, a homozygous frameshift mutation in CNTNAP2 was discovered in an Amish family with syndromic ASD (Cortical dysplasia focal epilepsy syndrome), a neuron migration disorder with epilepsy, language regression, hyperactivity, intellectual disability, and ASD55." (PMID 28358038, 2017). "In summary, while some variability in phenotype remains, it is clear that homozygous loss of CNTNAP2 results in a syndromic disorder characterised by severe intellectual disability, early-onset drug-resistant epilepsy, reduced or absent language, communicative impairments and autistic phenotypes." (PMID 26843181, 2016). "In a former study we reported on homozygous or compound heterozygous defects in CNTNAP2 or NRXN1 in four patients with intellectual disability and epilepsy, resembling Pitt-Hopkins syndrome (PTHS, MIM #610954)." (PMID 21827697, 2011). "This study exclusively uses Cntnap2 KO mice while ASD and epilepsy are genetically heterogeneous, and findings from one model may not generalize across other genetic backgrounds." (PMID 41408339, 2025). "Other patients with drug-resistant focal epilepsy and mutations in SCN1A, CNTNAP2, STBXP1 genes were not seizure-free after epilepsy surgery regardless of lesional status (including HS, focal cortical dysplasia, encephalomalacia present on MRI)." (PMID 35492509, 2022). "In human populations, CNTNAP2 heterozygous mutations do not always produce symptoms of ASD, while homozygous individuals for the mutation display ASD symptoms, along with epilepsy, facial dysmorphisms, severe intellectual disability and impaired language." (PMID 29740280, 2018).
epilepsy (continued). "Consequently, other studies reported CNV deletions in CNTNAP2 in schizophrenia, bipolar disorder, and ADHD; but also in neurological disorders, especially epilepsy, and language-related phenotypes." (PMID 30586385, 2018).
autoimmune encephalitis (82 papers, 2014 to 2026). Inflammation of the brain secondary to an immune response triggered by the body itself. "Genetic, immunological, and transcriptomic studies have implicated CNTNAP2 in a broad spectrum of neurological and psychiatric disorders, autoimmune encephalitis, and cancer." (PMID 42110583, 2026). "Anti-leucine-rich glioma inactivated-1 (LGI1) and anti-contactin-associated-protein-2 (CASPR2) autoimmune encephalitis (AIE) are common and characterized by pathogenic antibodies targeting neuronal autoantigens." (PMID 40094812, 2025). "The CNTNAP2 gene is also associated with anti-contactin-associated protein receptor 2 encephalitis, a type of autoimmune encephalitis, in which some patients exhibit Parkinsonian symptoms and ataxia." (PMID 40826483, 2025). "Autoantibodies against contactin-associated protein 2 (CASPR2) are usually associated with autoimmune encephalitis and neuromyotonia." (PMID 37599705, 2023). "This has been suggested or studied for abs against glycine receptors, glutamic acid decarboxylase and contactin-associated protein-2 (CASPR2) in the context of the clinical suspicion of autoimmune encephalitis." (PMID 29696018, 2018). "Complementary blood testing revealed a positive result for antineural antibodies to Contactin-associated protein 2 (CASPR2) and the patient received treatment for CASPR2 autoimmune encephalitis." (PMID 25434587, 2014). "Interestingly contactin-associated protein-like 2 (CNTNAP2), also known as Caspr2, is a member of the neurexin family and the target of autoantibodies thought to result in autoimmune encephalitis and neuromyotonia." (PMID 24466509, 2014).
autism spectrum disorder (65 papers, 2010 to 2026). A spectrum of developmental disorders that includes autism, and Asperger syndrome. "Variants in the CNTNAP2 gene, encoding the cell adhesion molecule CASPR2, have been identified as genetic risk factors for autism spectrum disorder (ASD)." (PMID 42249747, 2026). "Mutations in the Contactin-associated protein-like 2 (CNTNAP2) gene are associated with autism spectrum disorder (ASD), and ectodomain shedding of the CNTNAP2 protein plays a role in its function." (PMID 38424048, 2024). "Disruptions in the CNTNAP2 gene are known to cause language impairments and symptoms associated with autism spectrum disorder (ASD)." (PMID 36947880, 2023). "Mutations in CNTNAP2 have been linked to neurodevelopmental disorders like autism spectrum disorder (ASD), intellectual disability (ID), and specific language impairment (SLI)." (PMID 36340692, 2022). "The contactin-associated protein-like 2 (CNTNAP2) gene is associated with multiple neurodevelopmental disorders, including autism spectrum disorder (ASD), intellectual disability (ID), and specific language impairment (SLI)." (PMID 36340692, 2022). "The contactin-associated protein-like 2 gene, CNTNAP2, is a highly penetrant risk gene thought to play a role in the genetic etiology of language-related disorders, such as autism spectrum disorder and developmental language disorder." (PMID 35106542, 2022). "We utilized forebrain organoids generated from induced pluripotent stem cells of patients with a syndromic form of Autism Spectrum Disorder (ASD) with a homozygous protein-truncating mutation in CNTNAP2, to study its effects on embryonic cortical development." (PMID 34471112, 2021). "Only a single gene from the predicted off-target list, CNTNAP2, a gene implicated in autism-spectrum disorders, demonstrated differential expression following genome wide transcriptomics." (PMID 31925439, 2020). "It has also been reported that mutations in human CNTNAP2 gene, which encodes a contactin-2 binding protein, is associated with seizures, mental retardation, schizophrenia and autism spectrum disorder." (PMID 30515076, 2018). "These include a rare intronic heterozygous duplication (present in two individuals, including one affected) in contactin associated protein-like 2 (CNTNAP2), a gene associated with autism spectrum disorder." (PMID 25887117, 2015). "Specifically, a recent 9.4T MRS study reported a decrease in Glu/GABA in the prefrontal cortex of Cntnap2−/− mice, which has been implicated in autism spectrum disorder, compared to their wild-type littermates, while we recently reported a decrease in GABA/Glu in the thalamus of CHR vs. HC." (PMID 36555487, 2022). "Mutations in CNTNAP2 have been associated with a syndromic form of Autism Spectrum Disorder." (PMID 34471112, 2021). "Contactin-associated protein-like 2 (CNTNAP2) is associated with the development of Autism spectrum disorder (ASD) and the single-nucleotide polymorphism rs2710102 (G/A) of CNTNAP2 is suggested to contribute to sub-threshold social impairments and intellectual disabilities." (PMID 34898614, 2021). "Interestingly, several genes (Adcyap1, Cntnap2, Grid1, Nrxn1, Nrxn3, Ucn, Tbx1, and Nr2e1), that are associated with disorders, stress response, social behaviors or autism spectrum disorders, are up-regulated specifically in the hippocampus of Del/+ mice." (PMID 28704368, 2017). "Cntnap2 is strongly associated with autism spectrum disorders, shown in previous studies." (PMID 28610618, 2017). "BACKGROUND: Autism spectrum disorder (ASD) is a neurodevelopmental disorder with a strong genetic component, and over a thousand associated genes have been identified, including CNTNAP2 and SHANK3." (PMID 42010670, 2026). "The homozygous Cntnap2 knockout (KO) rat is a well-established genetic model for neurodevelopmental disorders, exhibiting core features of autism spectrum disorder (ASD), including impaired sensory processing and sensorimotor gating." (PMID 40134417, 2025).
autism spectrum disorder (continued). "Herein we report two sisters with a homozygous deletion affecting the CNTNAP2 gene and a phenotype including dysmorphic features, severe intellectual disability, early onset seizures, autism spectrum disorder and language impairment." (PMID 26843181, 2016). "In addition to SRD, it has also been associated with autism spectrum disorder, ASD, intellectual disability, ID, language impairment, and schizophrenia In a Chinese sample, the relationship between CNTNAP2 and risk of SRD was higher in females." (PMID 36675818, 2023). "Several genes were validated in APA sperm that were associated with autism spectrum disorder (CACNA1H, CNTNAP2, GRIN1, SHANK2, SHANK3, ZNF804A), schizophrenia (TCF3, ZNF804A), and bipolar disorder (COMT, DRD4, GRIN1, MBP, PRKCZ, SHANK2, TRPM2, ZNF804A), and in APA blastocysts (CACNA1H)." (PMID 32610362, 2020). "Interestingly, mutations in the CNTNAP2 gene, encoding CASPR2, are associated with focal epilepsy, schizophrenia, and autism spectrum disorder (ASD)." (PMID 32116982, 2019). "Considering that a large proportion of autistic patients show language impairments and most individuals with homozygous mutations in CNTNAP2 manifest autistic features, several studies investigated the potential involvement of CNTNAP2 in autism spectrum disorder (ASD)." (PMID 30586385, 2018). "For example, rats lacking the CNTNAP2 gene exhibit behavioral changes analogous to those seen in human autism spectrum disorder." (PMID 40906375, 2025).
schizophrenia (61 papers, 2010 to 2026). A major psychotic disorder characterized by abnormalities in the perception or expression of reality. "Genomic rearrangements and point mutations resulting in haploinsufficiency for CNTNAP2 have been associated with autistic spectrum disorders, schizophrenia and language disorders although this is not universally accepted." (PMID 39990522, 2025). "Migration defects have not been commonly noted in ASD but have been reported in studies of NDDs including schizophrenia, Rett syndrome, Down syndrome, Timothy syndrome, and CNTNAP2 mutation." (PMID 38525876, 2024). "The internal and overlapping deletions in the CNTNAP2 gene were associated with an increased risk of schizophrenia." (PMID 36980961, 2023). "This list also contains the FOXP1 and FOXP2 genes, which are required for development of speech and language in humans and interact with CNTNAP2, a member of the 47-gene list which is in the neurexin family of genes having known association with schizophrenia." (PMID 36711134, 2022). "CNTNAP2 was reported significantly associated with schizophrenia and major depression in the Han Chinese population and highly expressed in frontal and anterior lobes, striatum and dorsal thalamus." (PMID 30341038, 2018). "In fact, one of the signals we identified in CNTNAP2 is in full LD with a protective allele for schizophrenia and bipolar disorder (rs802568)." (PMID 26912479, 2016). "However, the phenotype associated with heterozygous CNTNAP2 mutation is complex as the severity of characteristics varies across patients and in some cases additional phenotypes are observed (e.g. Tourette syndrome, schizophrenia)." (PMID 26843181, 2016). "Disruption of Cntnap2 level leads to imbalanced excitatory and inhibitory neural networks, which are thought to be central to the pathophysiology of schizophrenia." (PMID 40548375, 2025). "Intriguingly, three thalamic regions primarily shown to suffer reductions in volume in schizophrenia patients, the MD, pulvinar and CM all highly expressed both CNTNAP2 and FOXP2." (PMID 39990522, 2025). "Mutations in CNTNAP2, the gene encoding Caspr2, have been associated with neurological disorders such as ASD, intellectual disability, schizophrenia, and dyslexia." (PMID 36737600, 2023). "Multiple pieces of evidence have linked CNTN2, CNTNAP2, GABBR2, and NTRK3 to neuropsychiatric disorders, including schizophrenia." (PMID 30323833, 2018). "There is also evidence that genetic variants common to schizophrenia and autism spectrum disorder, such as mutations in the SHANK3, NRXN1, and CNTNAP2 genes, may contribute to the occurrence of autistic phenotypes in some patients with schizophrenia." (PMID 40724876, 2025). "To find if Cntnap2 KO can be better explained by ASD than other neurological disorders, we carried out disease association analysis by using publicly available patients’ data from different neurological diseases (ASD and schizophrenia)." (PMID 36253443, 2023). "Though Dlx5 and Dlx6 have not been linked to specific disorders, Disc1 (disrupted-in schizophrenia-1) and Cntnap2 have similar functions in cortical interneurons." (PMID 33949949, 2021). "Here we report the largest sample investigated thus far in ASD and schizophrenia, which suggests that rare variants in CNTNAP2 do not play a major role in these two psychiatric disorders." (PMID 30586385, 2018). "Finally, we explored the potential impact of pathogenic ultra-rare variants (URV) in CNTNAP2 using available sequencing datasets of 4,483 patients with ASD and 6,135 patients with schizophrenia compared with 13,042 controls." (PMID 30586385, 2018). "Though the CAMs pathway was associated with schizophrenia in pathway level in both Chinese Han and European population, the significant associated CAMs genes in our dataset were different from those significant CAMs genes (HLA-DQA1, CDH4, NRXN1 and CNTNAP2) reported in European population." (PMID 26674772, 2015).
schizophrenia (continued). "The test included a dense coverage of SNPs across CNTNAP2: from 1,214 SNPs in MDD up to 12,264 SNPs in schizophrenia." (PMID 30586385, 2018). "In the network, candidate genes with nominal significance such as ANKS1B, CNTN2, CNTNAP2, GABBR2, NCOR2, and NTRK3 also may be involved in the pathology of schizophrenia." (PMID 30323833, 2018).
neuromyotonia (46 papers, 2012 to 2025). "This cohort study combined with a patient-led survey found that antibodies to the extracellular aspects of leucine-rich glioma inactivated protein, contactin-associated protein 2, and contactin 2 were variably present in 45% of patients with neuromyotonia." (PMID 30242309, 2018).
Morvan syndrome (42 papers, 2013 to 2026). Morvan syndrome is a rare, life-threatening, acquired neurologic disease characterized by neuromyotonia, dysautonomia and encephalopathy with severe insomnia. "Anti-contactin-associated protein 2 (CASPR2) antibodies are most common in patients with peripheral nerve hyperexcitability, including those with rare Morvan syndrome." (PMID 34421519, 2021). "In Morvan’s syndrome, characterized by peripheral nerve hyperexcitability, an association with the contactin-associated protein 2 (CASPR2) has been demonstrated." (PMID 26462472, 2015).